MIR4455 (microRNA 4455)
Synonyms: hsa-mir-4455
Gene: MicroRNA gene on chromosome 4 (184,938,383 to 184,938,440, reverse strand). Ensembl gene ENSG00000263458.
Homologues: Orthologues: chimpanzee MIR4455 (100% identical).